INS (insulin)
Diseases named in the same sentence as INS in open-access papers (continued):
Sharing a sentence is not in itself a finding about the gene and the disease.
metabolic disorders (continued). "Thus, IR-IRS1-GSK3β-MG53 formed a vicious cycle in the pathogenesis of metabolic disorders where aberrant insulin signaling led to hyper-activation of GSK3β, which in turn, phosphorylated MG53 and enhanced its E3 ligase activity, and further impaired insulin sensitivity." (PMID 36337049, 2022). "As Asians may suffer disproportionately from metabolic diseases due to lower insulin sensitivity (which triggers weight gain), the use of such drugs after testing in diverse Asian populations may relieve both metabolic and musculoskeletal stress due to weight loading on the hips and legs." (PMID 36143948, 2022). "Moreover, the integration of augmented secretion of inflammatory cytokines, altered mitochondrial metabolism and ectopic lipid deposition negatively blunt insulin signaling, coordinate systemic insulin resistance and increase probability of metabolic diseases and their complications." (PMID 36496995, 2022). "Overall, the study indicates that the benefits of ADF may be from the suppression on mitochondrial complex II activity by decrease of SDHAF4 and that modulation of hepatic SDHAF4 level could be a possible approach for managing insulin sensitivity and related metabolic disorders." (PMID 35037426, 2022). "Thus specific HMOs such as 2′-FL may constitute a means to correct gut dysfunction, dysmetabolism and insulin resistance, all of which drive the development of metabolic diseases including NAFLD." (PMID 35782914, 2022). "Pathophysiological markers of metabolic disease included the level of visceral and subcutaneous adiposity, adipocyte diameter, markers of chronic systemic inflammation (hsCRP), hepatic lipotoxicity (ALT, AST, GGT, hepatic lipids), atherogenic risk and whole-body insulin sensitivity (M-value)." (PMID 34603196, 2021). "Thus, decreased insulin clearance could be a relatively upstream factor that induces metabolic disease and an important therapeutic target for such diseases." (PMID 34572340, 2021). "Moreover, since regular exercise can reduce the levels of circulating fetuin-A, it may improve insulin sensitivity in patients with metabolic disorders." (PMID 33498410, 2021). "One potential mechanism by which the gut microbiome influences metabolic disease and T2D is via the fermentation of indigestible fibers into SCFAs (i.e., acetate, propionate, and butyrate) and others, and these metabolites can regulate blood glucose levels and insulin release." (PMID 33562070, 2021). "Together, we highlight that PPM1A may represent a therapeutic target for metabolic diseases in many aspects, such as increasing anti-inflammatory responses and enhancing the secretion of insulin-sensitizing adipokines which depends on dephosphorylation of PPARγ at Ser273." (PMID 32024237, 2020). "Thus, we hypothesize that IBIL might be a protective factor that enhances insulin sensitivity and serve as an insulin sensitizer, delaying the occurrence and development of metabolic diseases." (PMID 32802055, 2020). "Information on insulin, leptin, and cytokine signaling pathways within the CB might be of key importance and have significant clinical relevance as it might unravel therapeutic targets for the treatment of metabolic diseases." (PMID 32756352, 2020). "Minute ventilation increase during an hyperinsulinemic-euglycemic clamp and elevated plasma insulin levels increases minute ventilation independently of alterations in glucose levels, confirming the role of insulin as a contributor to CB dysfunction in metabolic diseases." (PMID 33353562, 2020). "Notably, siXIAP-treated mice exhibited higher glucose levels and dramatic shifts in area under curve (AUC) scores, suggesting that knockdown of XIAP in vivo may impair glucose tolerance and insulin sensitivity, further exacerbating metabolic disorders." (PMID 31841118, 2019).
metabolic disorders (continued). "Lack of n-3 PUFA effects on insulin sensitivity has been found in a meta-analysis, while association of short-term fish oil supplementation with increasing insulin sensitivity has been shown in another meta-analysis among people with metabolic disorders." (PMID 31888762, 2019). "In recent years, both insulin and C-peptide (a peptide cleaved from proinsulin and eventually released into the bloodstream in amounts equimolar with those of insulin) have been shown to exert various influences on anti-apoptosis, metabolic diseases, and nervous system diseases." (PMID 30430334, 2019). "A slight disruption of insulin secretion or organization of the pancreas may not impact the mechanism of glucose tolerance under standard conditions but may result in metabolic disease when caused by high-energy diet challenge, aging or genetic origin." (PMID 31717308, 2019). "Therefore, exploring the mechanisms of the hepatic insulin resistance could help us to provide new ideas for the treatment of metabolic diseases." (PMID 30949394, 2019). "While cell-specific differences in the regulation of FAK due to AMPK activation and insulin signalling are likely to exist, treatment strategies for metabolic disorders may be further validated through the study of the AMPK–FAK relationship in skeletal muscle, hepatic tissue or adipose tissue." (PMID 29022062, 2018). "Furthermore, some studies have proved that caffeine may play an important role in the regulation of insulin release and related metabolic disorders." (PMID 29562659, 2018). "In order to gain deeper understanding of dysregulation of glucose production in metabolic diseases, in the present study, we performed an unbiased phenotypic screening in primary human hepatocytes to discover novel mechanisms that regulate gluconeogenesis in the presence of insulin." (PMID 30131871, 2018). "Eventually, omega-3 fatty acids, which have been shown to increase insulin sensitivity in patients with metabolic disorders, may shift this relationship and alter autonomic regulation, thereby changing HRV parameters, which measure the activity of the autonomic nervous system." (PMID 29681953, 2018). "However, our study is one small step closer to interventional studies in humans that may evaluate the direct influence of myokines on insulin action and metabolic disease." (PMID 29445355, 2018). "Therefore, resistin impairment of insulin Akt/eNOS pathway may be an important convergence point linking CV and metabolic diseases." (PMID 30416448, 2018). "Thus, it is biologically plausible that fish oil supplementation could improve insulin sensitivity among people with metabolic disorders." (PMID 28673352, 2017). "Conditions which are present in ruminants and cause metabolic disorders and clinical disease near calving: negative energy balance, lipid mobilization, insulin resistance, and immunosuppression, closely resemble dysregulated metabolic systems in human diseases." (PMID 28261474, 2017). "Therefore, considering the differential aspects of IL-6 action under lean and obese conditions will contribute to our molecular knowledge how the low-grade metaflammation impacts on insulin signaling to ultimately result in the development of metabolic disorders." (PMID 28233125, 2017). "Conversely, short-term clinical studies show that a decrease in the postprandial glycaemic response combined with a non-exacerbated insulin demand could be beneficial for health maintenance and help reduce the risk of metabolic disease." (PMID 27388153, 2016). "Therefore, SCFAs have been proposed to play a key role in the prevention and treatment of inflammatory and metabolic disorders; for instance, butyrate derived from fibers improved insulin sensitivity and increased energy expenditure in a mouse model of diet-induced obesity." (PMID 27023530, 2016). "However, the role of adipocytes in linking energy metabolic disorders with insulin regulation is unknown in humans." (PMID 25743104, 2015).
metabolic disorders (continued). "Nevertheless, the improvements in aerobic capacity, whole body insulin sensitivity, and reduced adiposity in addition to the improvements in blood lipids following 10 weeks of group-based HIT will result in meaningful reductions in cardiovascular and metabolic disease risk." (PMID 26402859, 2015). "However, not all obese subjects are insulin resistant and have alterations in lipolysis and lipogenesis, and only those that develop cellular lipotoxicity are at risk of metabolic disorders." (PMID 26580649, 2015). "Therefore, we speculate that the potential molecular mechanism of ECD is to promote the CDKAL1 expression, ameliorate islet cell function, and raise insulin levels to regulate the metabolic disorder." (PMID 26504476, 2015). "Several studies that were carried out on humans and male C57BL/6 mice have shown that L-arginine supplementation may be considered a new treatment for metabolic disorders and also has an effect of lowering blood pressure, adipose tissue and weight and improves insulin sensitivity." (PMID 28751963, 2014). "Specifically, the individual roles of pro-inflammatory cytokines to modulate insulin sensitivity in skeletal muscle and adipose tissue should be identified to determine whether inflammation is indeed active in metabolic diseases similar to that observed in humans." (PMID 26486919, 2012). "Although the discriminative ability of serum insulin alone was moderate, this performance remains meaningful for clinical application, as NAFLD is a multifactorial metabolic disease and a single biomarker cannot fully capture all relevant determinants." (PMID 41560026, 2026). "IR often signifies a particular metabolic disorder characterized by elevated insulin levels, which may lead to neurodegenerative changes and persistent memory decline due to the long-term exposure of brain neurons to an environmental state of elevated insulin levels." (PMID 40800025, 2025). "Previous research has demonstrated that GDF-15 affects metabolism and insulin sensitivity by activating GFRAL, suggesting its involvement in metabolic disorders, oxidative stress responses, and inflammation." (PMID 41019919, 2025). "In metabolic diseases, CUL4B regulates adipose tissue and insulin sensitivity, with its depletion improving metabolic phenotypes." (PMID 40230836, 2025). "Our analysis of the correlation between mtDNA copy number and insulin signalling pathway gene expression in VAT and SAT revealed that VAT has a greater impact on metabolism and is more actively involved in metabolic disorders." (PMID 40806527, 2025). "Expanding these investigations to include other metabolic markers, such as lipid profiles and insulin sensitivity, will further advance the translational potential of cannabinoid-based therapies for IBD and related metabolic disorders." (PMID 40005963, 2025). "Also, Zlatkina, in her 2016 paper, concludes that increased blood serum VASP levels may precede changes in insulin levels in children, and that monitoring of VASP levels may allow a group at high risk of developing metabolic disease and hypertension in the future to be more quickly identified." (PMID 40491594, 2025). "In any case, future studies should aim to elucidate the molecular pathways involved, particularly those related to insulin signaling, inflammation, and mitochondrial function, to better understand the therapeutic potential of C-LMW in metabolic diseases." (PMID 41009711, 2025). "The molecular mechanism through which insulin quickly reduces ZAG expression warrants further research, specifically with broader cohorts with metabolic diseases, mechanistic studies, and potential therapeutic targets." (PMID 40564902, 2025). "Moreover, investigating orientin’s influence on systemic oxidative stress, insulin sensitivity, inflammatory markers, and adipose tissue remodeling in vivo would provide critical translational insight and support the development of orientin-based therapies for metabolic disorders." (PMID 40725115, 2025).
metabolic disorders (continued). "This study provides new insights into the complex interplay between insulin and ZAG in regulating energy balance and highlights the potential of ZAG as a therapeutic target in metabolic diseases." (PMID 40564902, 2025). "In metabolic disease, this microbial endotoxemia triggers systemic inflammation via Toll-like receptor 4 (TLR4) and NF-κB signaling, contributing to insulin resistance and tissue damage." (PMID 41374093, 2025). "To elucidate the interplay between DKK1, metabolic disorders, and IR in PCOS patients, we concurrently measured the levels of circulating DKK1 and Adipoq, an insulin‐sensitive molecule." (PMID 41320970, 2025). "The treatment downregulated PGC-1α while activating insulin signaling (p-p38MAPK/p-AKT/p-AS160) and GLUT4 translocation, suggesting therapeutic potential for metabolic disorders." (PMID 41044789, 2025). "Our results on serum proteins provide evidence for the role of the PI3K protein family being responsible for abnormal metabolic disease downstream of PI3K in the glucose, insulin, and lipid signaling pathways." (PMID 38542788, 2024). "This indicates that the underlying mechanisms—reduced insulin levels, enhanced lipolysis, and improved lipoprotein particle profiles—may extend to metabolic disturbances beyond T2DM, making low-carbohydrate dietary interventions relevant for a variety of endocrine and metabolic disorders." (PMID 39834467, 2024). "Accumulation of ceramide species inhibits insulin signaling along the Akt-PKB pathway and these lipids are strong biomarkers of metabolic disease." (PMID 39254086, 2024). "Due to the systemic effects of metabolic disorders, NAFLD pathology impairs lipid metabolism and insulin sensitivity, increases oxidative stress and systemic inflammation, exacerbates liver lipid deposition, and cardiovascular complications." (PMID 38173037, 2024). "In accordance, metabolic blood markers glucose, insulin, and HOMA-IR also exhibit increased values at metabolic disease presence." (PMID 39449123, 2024). "Insulin may act on mitogen-activated protein kinase (MAPK)/extracellular signal-regulated kinase (ERK), which mediates signals to mainly regulate cell growth and proliferation; in insulin resistance, these mediators are impaired and may provoke metabolic diseases and CV-associated alterations." (PMID 38790648, 2024). "In our previous studies, we found evident improvements in triglycerides, insulin, and glycemia in strength athletes and partially in cyclists who underwent the same dietary protocol of TRE and were free of metabolic diseases." (PMID 39614235, 2024). "However, it is important to perform further epidemiological and molecular studies to confirm the effects of Cu on metabolic diseases and understand its role as one of the possible markers of IR pathophysiology that could be intervened to improve insulin signaling." (PMID 38786759, 2024). "This disruption occurs through increased synthesis of the PERIOD protein via insulin and IGF-1 receptor signaling, ultimately resulting in metabolic disorder." (PMID 38409117, 2024). "In metabolic diseases, HMGA1 regulates insulin signaling pathways, affecting insulin sensitivity and glucose metabolism homeostasis." (PMID 39507236, 2024). "Indeed, the establishment of systemic inflammation, including high circulating levels of inflammatory cytokines (like TNF-a, IL-1B, 6, and 17), as well as an increased immune infiltrate in insulin-dependent tissues, without causing tissue damage, is the distinctive trait of metabolic disorders." (PMID 38337675, 2024). "In recent years, increasing attention has been given to the role of inositol in the pathogenesis of some metabolic diseases, such as MetS, T2D, and PCOS, which are all conditions related to altered insulin sensitivity." (PMID 36826058, 2023).
metabolic disorders (continued). "Ascorbic acid appears to lower blood glucose increase insulin synthesis and secretion, and enhance insulin sensitivity, all of which are beneficial in T2DM, AD, and other metabolic diseases." (PMID 36902074, 2023). "Hyperinsulinemic euglycemic clamp (HEC) technology and the insulin suppression test (IST) were used in the pathogenesis research and new drug evaluation of various metabolic diseases." (PMID 37893213, 2023). "Pregnancy-related metabolic disorders, such as GDM, occur when ROS prevents insulin from facilitating cellular glucose uptake, subsequently leading to insulin resistance." (PMID 36829900, 2023). "An improved comprehension of SGLT2 inhibitors and their impact on insulin sensitivity holds promise for enhancing treatments for T2DM and metabolic disorders." (PMID 37998523, 2023). "EA can regulate peripheral metabolic disorders, significantly increase IRS-1 levels, promote AKT phosphorylation, and enhance insulin sensitivity." (PMID 38283741, 2023). "This regulatory feedback loop of insulin signaling is essential for adipogenesis and in the maintenance of WAT and BAT function in restoring metabolic homeostasis and preventing systemic metabolic diseases." (PMID 36241662, 2022). "As a result of this cross-sectional analysis, tryptophan concentrations appear to be independent of the grade of adiposity but still correlate with metabolic disease markers like HOMA-IR, insulin, and c-peptide, as did kynurenine concentrations." (PMID 35057467, 2022). "Our findings delineate a mechanism in which LLPS of IRS-1-mediated signalosomes serves as an organizing center for insulin/IGF-1 signaling and implicate the role of aberrant IRS-1 LLPS in metabolic diseases." (PMID 35764611, 2022). "In the present study, the onset and progressing severity of type 2 DM induced with the use of HFD and STZ induced severe metabolic disorders including elevated FBG levels and insensitivity of the hippocampal cells to blood insulin." (PMID 37786742, 2022). "IXA4 treatment also improved insulin regulation and secretion in the pancreas, uncovering a new mechanism through which pharmacologic IRE1 activation aids to restore homeostasis in metabolic disease." (PMID 35105890, 2022). "And systemic metabolic disorders of glucose and lipid were also amplified by the miR-665-3p agomir upon HFD stimulation, as evidenced by the increased levels of FBG, serum insulin, HOMA-IR, serum TG and TC." (PMID 35038955, 2022). "Since deteriorated insulin action and mitochondrial dysfunction in the brain are involved in this disease development, lack of Hsp10 could be implicated in connecting metabolic disorders and neurodegenerative diseases." (PMID 33946318, 2021). "An increasing number of studies report that the lipid metabolism-related signaling pathway and insulin signaling pathway could be regulated by natural compounds, which indicates that traditional herbal medicines are potential alternatives or supplements to treat metabolic diseases." (PMID 33936248, 2021). "In a typical model for metabolic disease, DIO mice, we found that defective insulin secretion is compensated by increased insulin content." (PMID 34205530, 2021). "Despite the glucose-lowering effects of ROCK1 inhibition in mouse models of metabolic disease, ROCK1 inhibition in cultured adipocytes impairs insulin-stimulated glucose uptake." (PMID 33633690, 2020). "JNK is one of the major inflammatory cytokines to inhibit insulin signaling via the induction of IRS1 phosphorylation at serine residues in hypertensive and metabolic diseases." (PMID 32851077, 2020). "The fasting blood glucose (FBG), body weight, and insulin, TG, TC and MDA levels were further studied to reveal the effects of BAI-LZM on metabolic disorder in diabetic rats." (PMID 32398108, 2020). "Considering its reported effects on insulin, the GLP-1/GLP-1R axis is a promising drug target for metabolic diseases." (PMID 32655632, 2020).